PDGFRA (platelet derived growth factor receptor alpha)
Diseases named in the same sentence as PDGFRA in open-access papers (continued):
Sharing a sentence is not in itself a finding about the gene and the disease.
tumor (continued). "Recurrence within CNS was more common in patients with high primary tumour cell PDGFRα expression, 4/15 (27%) versus 2/58 (3%), P = 0.01." (PMID 29380207, 2018). "It inhibits platelet-derived growth factor receptor alpha, leading to the inhibition of tumor cell proliferation, angiogenesis, and metastasis." (PMID 30588358, 2018). "In a phase I study of BLU-285, all 31 patients with D842V PDGFRA GISTs demonstrated a tumor response." (PMID 30450193, 2018). "For both CCND1 and PDGFRA, staining within Group 2 tumours was most prominent within the “oligodendrocyte-like” cell population often described within DNETs." (PMID 29058119, 2018). "Surprisingly, we also found that there were partial losses of certain oncogenes (FGFR1, PDGFRA, and so on) and amplifications of certain tumor suppressors (NBN, EXT1, and so on) in these cell lines." (PMID 29880898, 2018). "Sunitinib treatment of mECK36 tumors showed a stronger anti-tumor effect than Imatinib, leading to a complete inhibition of tumor growth, which occurred with complete blockage of PDGFRA phosphorylation." (PMID 29985958, 2018). "Tumour cells showed high expression of PDGFRα in 100 (20%) and PDGF-CC in 103 (21%) of the evaluated primary tumours." (PMID 29380207, 2018). "The PDGF-CC ligand was discovered towards the end of the 1990s and it has been shown to be involved in tumour growth by paracrine signalling through PDGFRα in malignant melanoma and cervical carcinoma." (PMID 29380207, 2018). "Almost all tumours with high stromal cell PDGFRβ and high tumour cell PDGF-CC also had high PDGFRα, either in stromal or tumour cells." (PMID 29380207, 2018). "Immunostaining of the mCAF markers Fibulin-1 and PDGFRα showed high prevalence of positive cells at the invasive front of tumors, in contrast to the relatively low abundance of mCAFs in the tumor core." (PMID 30514914, 2018). "Secondary to these findings, imatinib mesylate (Gleevec®) therapy, which can inhibit the intracellular kinase activities of CD117 and PDGFRa, has been manifested to increase the overall tumor control rate of GIST by 85%." (PMID 28376760, 2017). "This surprising reduction in tumor growth by constitutively active PDGFRA can be explained by the induction of senescence through a supra-optimal Erk and Akt downstream signal." (PMID 28894696, 2017). "Expression of PDGFRα in the tumor correlated with increased collagen α1(I), lecithin retinol acyltransferase, and smooth muscle α-actin suggesting increased HSCs in tumor sites." (PMID 28465473, 2017). "Another possible explanation is an artificial selection of cells with activated c-MET or PDGFRα from heterogeneous cell populations within a tumour during cell-line establishment." (PMID 28511645, 2017). "Mutations of KIT and PDGFRA are the most common causes of GIST, which can develop in any part of the gastrointestinal tract with a different prognosis dependent on the tumor location." (PMID 28589146, 2017). "While several studies reported that PDGFRα positive cells in tumor sites are malignant cells themselves, another study argued that those were invaded non-parenchymal cells that showed PDGFRα positive." (PMID 28465473, 2017). "PDGFRα and PGDFRβ signalling indirectly promotes tumour development by activating the mesenchymal cells in the tumour microenvironment and directly stimulates the growth of malignant cells." (PMID 28511645, 2017). "Immunohistochemical results showed a marked downregulation of PDGFRα expression in the tumor samples from animals treated with DHA." (PMID 29387451, 2017). "These experimental results have demonstrated the significance of c-MET and PDGFRα signalling for growth and/or survival of SS tumours." (PMID 28511645, 2017). "We tested the antitumour effect of TAS-115 against Yamato-SS (c-MET-dependent SS cells) and SYO-1 (PDGFRα-dependent SS cells) xenograft tumours." (PMID 28511645, 2017).
tumor (continued). "ERMS tumor also harbored additional gene alterations: low amplification of EGFR, PDGFRA, and CDK4 genes, and loss of heterozygosity of CDKN2A and 19q12-19q13.43 chromosomal regions." (PMID 28222777, 2017). "IHC analysis revealed that tumor tissues derived from mice with injection of PDGFRα-overexpressing Tsc2−/− MEFs exhibited much stronger staining for Ki-67 than those in the control group." (PMID 28903387, 2017). "PDGFB and PDGFRB are less expressed relatively to PDGFC in perinecrotic zone, and also in comparison to PDGFRA in cellular tumour block." (PMID 29127351, 2017). "Using liver samples of 95 patients, tissue microarray was constructed and immunohistochemical study of PDGFRα was conducted in both tumor and non-tumor sites." (PMID 28465473, 2017). "Tumor and normal DNA from a GIST case carrying the IM-resistant PDGFRA D842V mutation was analyzed by whole exome sequencing (WES) to identify additional potential targets for therapy." (PMID 28768491, 2017). "Tumor site PDGFRα expression was correlated with increased collagen α1(I) (Col1α(I)) mRNA on tumor site." (PMID 28465473, 2017). "In this study we characterize wide-ranging patterns of EGFR and PDGFRA co-expression among single cells sorted from patient-derived GBM tumor sphere (GTS) lines representing a selection of the most common genotypes, not restricted to co-amplified tumors." (PMID 28831081, 2017). "In conclusion, c-MET and PDGFRα signalling are essential for the growth and/or survival of SS tumours." (PMID 28511645, 2017). "We compared the distributions of reads mapping exons 8 and 9 in PDGFRA between tumor samples and the blood controls in TCGA data." (PMID 27888226, 2016). "In the same experiment, we observed a transient downmodulation of hypo-Rb1, which represents inactivation of the tumor suppressive function of Rb1 downstream of the PDGFRα/PDGFAA axis." (PMID 27344175, 2016). "The levels of NOTCH1 and PDGFRB in GBM were significantly higher than those in non-tumor controls (P values were 0.0085 or 0.019, respectively), whereas PDGFRA levels were similar (P value was 0.58), consistent with previous reports." (PMID 27863440, 2016). "A second encouraging result of combining ATM and PDGFRA inhibitors is that they not only reduce tumor cell proliferation, but also potently induce cell death." (PMID 26984279, 2016). "The activity of regorafenib, M‐2, and M‐5 at PDGFRα and FGFR2, which are associated with maintenance of the tumor microenvironment 16, was also assessed in cell‐based assays." (PMID 27734608, 2016). "We performed molecular characterization of the matched tumor and the primary cell culture, and describe the successful targeting of PDGFRA with clinically available receptor tyrosine kinase inhibitors." (PMID 27582545, 2016). "We stratified DOG1 positive patients in relation to the Allred scoring system to identify those with a higher risk of recurrence; in our study patients with a strong DOG1 expression, tumor size ≥ 5 cm and mutations of KIT or PDGFRA had a worse prognosis." (PMID 26867653, 2016). "Previous studies showed that either genetic or pharmacological targeting of PDGFRβ or PDGFRα inhibited self-renewal, survival, tumor growth and invasiveness of GBM CSC." (PMID 27344175, 2016). "Previous large scale genomic characterizations of pediatric HGG have shown that PDGFRA is a frequent tumor driver." (PMID 27582545, 2016). "The PDGFR amplification was confirmed by IHC, showing 90% PDGFRα positive (3+ expression in 90% of tumor cells)." (PMID 26510912, 2015).
tumor (continued). "Characteristically these neoplasms contain activating mutations in KIT, or less commonly platelet derived growth factor receptor alpha (PDGFRA)." (PMID 25694839, 2015). "On the other hand, a qPCR analysis using mouse-specific primers revealed that the expression of VEGFA, FGF2, FGFR2 and platelet-derived growth factor receptor A (PDGFRA) was upregulated in the bevacizumab-treated tumour stroma." (PMID 26635184, 2015). "Intriguingly, enhanced benefit with hundred per cent tumor regression was observed in both PDGFRA amplified models which translates into elevated levels of activated PDGFRA receptors, either in combination with irinotecan in IGRM57 or irradiation in IGRG93." (PMID 26599335, 2015). "We also assessed the effect of OKN-007 regarding the immunoexpression of tumor signaling molecules such as PDGFRα, SULF2, and decorin in the IC-3752GBM pGBM model." (PMID 26248280, 2015). "As firstly identified by the present study, both human and mouse HCC tissues with high PDGFRα expression displayed significantly higher MVD than those with low PDGFRα expression, respectively, implying a potential role of PDGFRα in tumor angiogenesis." (PMID 25333264, 2014). "The pro-angiogenic growth factor receptor, PDGFRα, had increased cpAC tumor mRNA, protein expression and phosphorylation when compared to the normal lung tissue biospecimens." (PMID 24423144, 2014). "The odds ratio (OR) of c-KIT, VEGFR2 and PDGFRα positivity, adjusted for tumor characteristics, was 6.8, 3.6 and 1.3 times higher for TNBC than for non-TNBC." (PMID 25025175, 2014). "Intriguingly, a recent study demonstrated that PDGFRα staining predominantly located in small blood vessels instead of tumor cells." (PMID 25333264, 2014). "The identification of the FIP1L1- PDGFRA fusion gene is significant since imatinib has excellent efficacy at low doses (100-400 mg daily) in FIP1L1-PDGFRA-positive neoplasms." (PMID 24669761, 2014). "Since Imatinib targets both PDGFRα and PDGFRβ while Sunitinib and Regorafenib only target PGDFRβ, we anticipated that Imatinib would be the most effective inhibitor at suppressing tumor cell migration." (PMID 25253994, 2014). "In this retrospective study, tumor mutational testing for the oncogenic KIT and/or PDGFRA genes was able to be performed in only 12 of 41 (29%) of these rare patients with rectal GISTs." (PMID 24597959, 2014). "We further measured the MVD by immunostaining for CD31 in each tissue section, and significantly elevated MVD by 6 to 8-fold was noticed in the tumor foci of PDGFRα OE group compared with control group." (PMID 25333264, 2014). "Consistently, PDGFRα upregulation was observed on endothelial cells from highly metastatic tumor xenografts and appeared to have a predictive value for HCC recurrence." (PMID 25333264, 2014). "In order to utilize the phenomenon we have observed as a method for patient selection, one would need to monitor PDGFRα up-regulation in tumor biopsy specimens or to develop a noninvasive or surrogate method to detect PDGFRα up-regulation." (PMID 24732172, 2014). "Ten variants were identified from eight genes in both the tumor and normal groups (APC, EGFR, FGFR3, KDR, MET, PDGFRA, RET and SMO)." (PMID 25404506, 2014). "Inhibition of PDGFRα signaling has been used as an effective therapeutic strategy in diseases wherein such signaling is known to be important for tumor progression." (PMID 25149088, 2014). "Two cpACs had faint stromal staining for VEGF and PDGFRα whereas; PDGFRβ had distinct strong stromal tumor staining in 92% (11/12) with faint positive cytoplasmic staining and rare membranous staining of the neoplastic cells in 75% (9/12)." (PMID 24423144, 2014).
tumor (continued). "High PDGFRα expression led to substantially increased tumor volume and tumor weight, as well as increased CD31 expression." (PMID 25333264, 2014). "In the present case, the large size, presence of necrosis and positive expression of CD117, CD34 and PDGFRA in the tumor cells suggested a malignant potential, while the low mitotic rate (<10/50 HPF) did not favor this conclusion." (PMID 24137442, 2013). "The concordance between detection of 3 exploratory genes (except PDGFRα) and tumor markers in patient samples was 80% (8/10) using the multimarker qRT-PCR assay." (PMID 23990866, 2013). "The subtypes are not as well defined in pediatric GBM where genetic profiling revealed PDGFRα as the predominant focal amplification target and gene expression analyses indicated deregulation of PDGFRα signaling plays an important role in tumor development." (PMID 23450706, 2013). "Bulk profiling of tumour specimens suggests that only PDGFRA is common to 4q12 amplified cases, with 39% of these harbouring PDGFRA amplification alone, 23% including PDGFRA and KIT, and 38% encompassing all three RTKs." (PMID 23990986, 2013). "In the xenograft, as in the primary tumor, positive PDGFRA expression was seen, both in tumor cells and blood vessels." (PMID 23527265, 2013). "Typically, PDGFRα is highly expressed by tumour cells and PDGFRβ is preferentially expressed by vascular endothelial and mural cells within tumours." (PMID 23638177, 2013). "As for the other three possible tumor subtypes, ALDH2 was associated with KIT exon 11 insertions (p = 0.03) and the null GSTT1 genotype was associated with PDGFRA-mutated tumors (p = 0.04)." (PMID 23637977, 2013). "The transmembrane receptor tyrosine kinase platelet-derived growth factor receptor-α (PDGFRα) plays an important role in human carcinogenesis, both as a direct target on tumor cells and as a mediator of stromal support for cancer cell growth." (PMID 23990866, 2013). "This is despite the relative clinical outcomes, with tumours amplified for two or three genes doing significantly worse than those amplified for PDGFRA alone or harbouring normal copy number (p = 0.0159, log-rank test)." (PMID 23990986, 2013). "Those tumours with concurrent PDGFRA and KIT amplification fell in between these figures (3/7, 42.9%)." (PMID 23990986, 2013). "Immunostaining for ASMA and PDGFRα yielded a similar pattern, with positive cells being predominantly elongated and located within streaks bridging nests of tumour cells." (PMID 22432595, 2012). "We found around 94% of tumor foci in KO to be strongly positive for PDGFRα in the cytoplasm of tumor cells." (PMID 22761897, 2012). "Although PDGFRA was overexpressed in most of the tumors compared to normal brain, this overexpression was significantly stronger in the group 1 tumours (p = 0.0055)." (PMID 22389665, 2012). "The two tumor foci that were β-catenin-positive in the KO livers were simultaneously positive for PDGFRα." (PMID 22761897, 2012). "Overall, PDGFRα expression was higher and also in greater numbers of tumor foci in the KO as compared to the WT 8 months after DEN/PB exposure." (PMID 22761897, 2012). "While the messages for VEGFR2, Kit, PDGFRα and PDGFRβ were detected in all tumor samples, only PDGFR-α and VEGFR2 expression were detected in all AGASACA and TC tumor cells by IHC." (PMID 22630170, 2012). "We next investigated PDGFRα signaling, which has been implicated in HCC and is involved in tumor growth, angiogenesis, and maintenance of tumor microenvironment." (PMID 22761897, 2012). "In the current study, we found PDGFRα to be expressed in all tumor cells of all canine TC samples, while PDGFRβ was primarily expressed in the tumor stroma by IHC." (PMID 22630170, 2012). "In an experimental model it was shown that VEGF-null cells require PDGFRα for the recruitment of fibroblast in the tumor stroma." (PMID 27713269, 2010).
tumor (continued). "On the other hand, high expression of PDGF-A, -B, -D and PDGFRα in tumor stroma are correlated with good prognosis." (PMID 27713269, 2010). "PDGFRα is a receptor tyrosine kinase involved in tumor angiogenesis and maintenance of the tumor microenvironment." (PMID 19793339, 2010). "In human glioblastoma, PDGFRα is expressed by tumor cells and PDGFRβ is expressed by ECs of the newly-formed blood vessels." (PMID 27713269, 2010). "PDGF-A was demonstrated to be the major stromal fibroblast chemotactic factor produced by tumor cells and disrupting the paracrine signaling with PDGFRα significantly reduced tumor growth by inhibiting both tumor cells growth and angiogenesis." (PMID 27713269, 2010). "This is also supported by the inhibition of tumor growth and angiogenesis by PDGFRα in an experimental model of malignant melanoma." (PMID 27713269, 2010). "In 14 out of 15 GISTs with a KIT mutation and in 2 out of 10 GISTs with a PDGFRA mutation, the relative expression of KIT was 1.47 arbitrary units (a.u.)or greater, while in the remaining tumours, it was 0.37 a.u. or lower." (PMID 19943934, 2009). "In 22 cases, it was possible to analyse PDGFA and PDGFRA expression in both primary and recurrent tumours." (PMID 19707201, 2009). "Of note, 80 of 91 (88%) assessable tumours were positive for PDGFRα, whereas 47 of 67 (70%) assessable tumours expressed PDGFRβ." (PMID 19904263, 2009). "In the present study, we detected PDGFRA overexpression in all cases, either in the neoplastic or stromal component of tumours." (PMID 19563658, 2009). "In all but one case (tumours 110 and 111) primary and recurrent tumours displayed identical PDGFRA copy number status." (PMID 19707201, 2009). "PCR–SSCP analysis for PDGFRA gene mutations in exons 12, 18 and 23 produced optimal results in 86 cases, 30 of which were PDGFRA-positive tumours." (PMID 19707201, 2009). "When tumours were classified into the three major groups according to their histogenesis (astrocytic, oligodendroglial and mixed), only PDGFRA expression was statistically significantly correlated with astrocytic lineage (P<0.001)." (PMID 19707201, 2009). "Among the probe sets with detectable expression levels, the non-parametric Kruskal-Wallis test revealed 970 (311 with FC>2; FC = fold change) probe sets differentially expressed between tumours with KIT and PDGFRA mutations." (PMID 19943934, 2009). "In 12 cases, data on PDGFRA amplification status in both the primary and recurrent tumours were available." (PMID 19707201, 2009). "These tumours are defined as specific, generally Kit (CD117)-positive and Kit or platelet-derived growth factor receptor alpha (PDGFRA) mutation-driven tumours." (PMID 20062725, 2009). "Tumor size, location, mitotic rate, C-KIT and PDGFRA genotype are the major determinants of malignant potential of the tumor which have significant impact on prognosis." (PMID 18775061, 2008). "The 5-year overall survival rates for patients with tumours with low, moderate and high PDGFRA expression were 49% (95% CI, 34–63%), 51% (46–57%) and 31% (19–43%), respectively." (PMID 15583695, 2004). "The 5-year disease-free survival rates for patients with tumours with low, moderate and high PDGFRA expression were 90% (95% CI, 76–100%), 70% (64–77%) and 39% (21–57%), respectively." (PMID 15583695, 2004). "Tumour-derived DNA from his GIST demonstrated a somatic PDGFRA driver mutation, and SDH staining was preserved, indicating a sporadic PDGFRA-driven GIST rather than a classical SDHA-deficient tumour." (PMID 41635891, 2026). "The NCR does not capture some clinicopathologic information specific to GIST, including tumor–node–metastasis stage, risk classification of resected GIST, genetic mutations of KIT and PDGFRA, specific drug names and doses of chemotherapy, and the efficacy and safety of each treatment." (PMID 40673479, 2025).